PDCD4 (programmed cell death 4)
Diseases named in the same sentence as PDCD4 in open-access papers (continued):
Sharing a sentence is not in itself a finding about the gene and the disease.
melanoma (25 papers, 2015 to 2025). A malignant, usually aggressive tumor composed of atypical, neoplastic melanocytes. "CASC15 is an oncogenic lncRNA associated with melanoma progression, which activates the Wnt/β-catenin pathway and inhibits expression of PDCD4 by recruiting EZH2 and increasing H3K27me3 level at its promoter." (PMID 35159386, 2022). "Given that high PDCD4 levels are associated with improved 5-year survival in primary melanomas, we evaluated additional tissue variables for prognostic significance using t-tests." (PMID 33801444, 2021). "Our study of paired cranial and extracranial human melanomas showed that high PDCD4 expression in cerebral specimens is significantly associated with improved survival, suggesting a role for PDCD4 loss in dysregulating melanoma brain metastasis." (PMID 33801444, 2021). "However, increased stromal PDCD4 expression in primary melanomas was associated with an improvement in 5-year survival." (PMID 33801444, 2021). "In our previous study of cerebrotropic melanomas, we found the mechanism accounting for PDCD4 loss or suppression was post-translational, via proteasomal degradation and likely regulated by the crosstalk of PLEKHA5, a mediator of brain metastasis, with the PI3K/AKT and ubiquitin-proteasome pathways." (PMID 33801444, 2021). "The expression of the tumour suppressor protein PDCD4 (Programmed Cell Death 4) correlates with a good prognosis in melanoma and is upregulated in KSR1−/− cells." (PMID 37511580, 2023). "While targeting programmed cell death (PDCD) 1 is a central treatment against melanoma, little is known about the related protein PDCD4." (PMID 33801444, 2021). "We defined differences in melanoma PDCD4 subcellular localization (either total cellular or nuclear-only) during oncogenesis, evaluated its presence on tumor-infiltrating immune cells, and determined its impact on survival." (PMID 33801444, 2021). "As previously reported, staining for PDCD4 was cytoplasmic and/or nuclear in melanoma cells as well as on immune-infiltrating cells in the stroma." (PMID 33801444, 2021). "Our past studies suggest PDCD4 interacts with Pleckstrin Homology Domain Containing A5 (PLEKHA5) to influence melanoma brain metastasis outcomes, as high intracranial PDCD4 expression leads to improved survival." (PMID 33801444, 2021). "It will be critical to understand how PDCD4 can be employed as a prognostic biomarker in intracranial disease and how it can be therapeutically targeted to improve survival in melanoma patients." (PMID 33801444, 2021). "Here, we found that PDCD4 is restricted to the nuclear compartment in normal skin but transitions mainly to cytoplasmic expression in nevi, primary melanomas, and metastatic melanomas, suggesting a role in melanoma disease progression." (PMID 33801444, 2021). "Based on this observation, our current studies evaluated PDCD4 expression either overall in the S100-positive melanocyte/melanoma (simultaneous measurement of expression in the cytoplasm and nuclei—‘total PDCD4′) or the DAPI-positive nuclei (‘nuclear PDCD4′)." (PMID 33801444, 2021). "The utility of PDCD4 as a biomarker for melanoma response to current checkpoint inhibitors will need to be further validated as a result." (PMID 33801444, 2021). "We aimed to define the subcellular distribution of PDCD4 in melanoma and in the tumor microenvironment during neoplastic progression and its impact on clinical outcomes." (PMID 33801444, 2021). "Little is known about the subcellular localization and function of programmed cell death 4 (PDCD4) in melanoma." (PMID 33801444, 2021). "We offer insight into the subcellular distribution of PDCD4 in melanoma progression and delineated differences between extracranial and intracranial metastases." (PMID 33801444, 2021). "We previously noted two distinct PDCD4 staining patterns in metastatic melanoma tissues: cytoplasmic and nuclear or nuclear only." (PMID 33801444, 2021).
melanoma (continued). "In a small cohort of primary melanomas, low cellular PDCD4 mRNA levels correlated with increased tumor size, high Clark level, and lymph node metastases." (PMID 33801444, 2021). "To further characterize the immune subtypes in melanoma brain metastasis that express PDCD4, we used 10X transcriptomic single-cell sequencing to identify key immune populations." (PMID 33801444, 2021). "Using CD45+-sorted immune cells in the brain of a resected melanoma brain metastasis, we found that PDCD4 is expressed on CD8+ T cells and NK cells as anticipated, but also demonstrate novel expression on B cells and mast cells." (PMID 33801444, 2021). "We previously reported that PDCD4 staining was predominately cytoplasmic in cerebral compared to extracerebral melanoma metastases." (PMID 33801444, 2021). "Although overall PDCD4 expression decreases during the transition from nevi to melanoma, we believe the shuttling from nuclear to cytoplasmic subcellular localization is more pathologically relevant in disease progression." (PMID 33801444, 2021). "miR-21-5p downregulates the expression of tumor suppressor genes, such as PTEN (phosphatase and tensin homolog), Sprouty1 and Sprouty2, and PDCD4 (programmed cell death protein 4), thereby promoting the initiation and progression of malignant melanoma." (PMID 33023062, 2020). "It was shown that the consensus sequence of p90 ribosomal S6 kinase (RSK) is RXRXXS/T as same as that of p70S6K1 and the enzyme phosphorylates, the Ser76 and Ser457, as well as Ser67 of human PDCD4-protein in melanoma cells." (PMID 31075975, 2019). "Knockdown of miR‐21‐5p in melanoma cell lines reduces cell proliferation and migration, and promotes apoptosis by increasing the expression of programmed cell death 4 (PDCD4), phosphate and tensin homolog (PTEN) and BTG family member 2 (BTG2)." (PMID 30499222, 2019). "PDCD4 is suppressed in ~25% of human cell lines that are established from advanced melanoma lesions." (PMID 26116372, 2015). "Upregulation of miR-21 by targeting PDCD4 could enhance tumor size and metastasis in malignant melanoma." (PMID 35402235, 2022). "PDCD4 may be a potentially useful biomarker in melanoma to help guide our understanding of patient prognosis." (PMID 33801444, 2021). "We demonstrate differences in PDCD4 expression during neoplastic progression, with high tumor and stromal PDCD4 levels associated with improved survival in primary melanomas and in intracranial metastases, but not in extracranial metastatic disease." (PMID 33801444, 2021). "Additionally, higher PDCD4 expression was seen with higher Clark level and decreased microscopic satellites in primary melanomas." (PMID 33801444, 2021). "Methods to increase PDCD4 in those with melanoma brain metastases may also help improve disease response." (PMID 33801444, 2021). "Our study aimed to thoroughly characterize PDCD4 expression in human melanoma specimens and benign nevi and to evaluate the prognostic role of PDCD4 in tumor vs. immune-infiltrating cells using a large historical cohort of primary and metastatic melanoma specimens annotated for clinical outcome." (PMID 33801444, 2021). "MicroRNAs (miR), such as miRNA-21, are known to transcriptionally suppress several tumor suppressor genes, such as PTEN and PDCD4, and increased miRNA-21 augments metastatic burden in a B16 mouse melanoma model by promoting cancer cell proliferation, survival, and metastasis." (PMID 33801444, 2021). "High tumor and stromal PDCD4 levels are associated with improved survival in primary melanomas and in intracranial metastases, but not in extracranial metastatic disease." (PMID 33801444, 2021). "A recent study reported that miRNA-150 inhibitors could enhance the cell apoptosis of melanoma by targeting PDCD4." (PMID 31159463, 2019). "lncRNA CASC15 promotes melanoma progression by epigenetically regulating PDCD4." (PMID 31399501, 2019).
melanoma (continued). "Transcriptional repression by PDCD4 and CADM1 leads to increased invasion and metastasis formation in melanoma cells." (PMID 35159386, 2022). "In B16 melanoma cells, it was shown that miR-21 promoted a metastatic behavior through the downregulation of many tumor suppressor proteins, including PTEN, PDCD4, and BTG269." (PMID 33980826, 2021). "Further studies are needed to define the interaction of PDCD4 and PLEKHA5 and to evaluate the utility of this pathway as a therapeutic target in melanoma brain metastasis." (PMID 33801444, 2021). "In human melanoma A375 cells, miR-21 promotes proliferation, migration, and suppresses apoptosis by inhibiting Sprouty 1 (SPRY1), programmed cell death 4 (PDCD4), PTEN and cyclin-dependent kinase inhibitor 2C (CDKN2C)." (PMID 32751207, 2020). "PDCD4 is a tumor suppressor downregulated or absent in multiple tumors such as melanoma, lung cancer, hepatocellular carcinoma, breast carcinoma, colorectal cancer, and gastric cancer." (PMID 33801444, 2021). "Based on single-cell sequencing data on a melanoma brain metastasis sample, we found that PDCD4 was also present on B cells and mast cells, which has never been previously reported." (PMID 33801444, 2021). "In melanoma, the clinicopathological significance and prognostic value of PDCD4 expression have not been thoroughly evaluated." (PMID 33801444, 2021). "Although expression changes have been associated with differences in melanoma aggressiveness in vitro, not much is known about the compartmentalization of PDCD4 expression in human melanoma tissue during metastatic progression." (PMID 33801444, 2021). "Only a handful of studies have evaluated PDCD4 expression in human melanomas, primarily using cell lines absent of clinical data." (PMID 33801444, 2021). "Melanoma metastases had increased stromal PDCD4 compared to primary lesions (non-paired t-test, p = 0.029)." (PMID 33801444, 2021). "A study showed decreased PDCD4 mRNA levels in melanoma compared to adjacent normal tissue but did not differentiate between nuclear vs. cytoplasmic PDCD4 compartmentalization." (PMID 33801444, 2021). "We found that PDCD4 is increased in the stroma of metastatic compared to primary melanoma, but expression did not translate into differences in survival." (PMID 33801444, 2021). "As we know that PDCD4 is expressed in cytotoxic CD8+ T cells, this may explain the improved survival in primary melanomas." (PMID 33801444, 2021). "We have now found that 5-year survival was improved in primary melanoma cases with high PDCD4 expression, but no survival differences were seen when evaluating PDCD4 expression in metastatic disease using a TMA primarily consisting of extracranial metastases." (PMID 33801444, 2021). "In melanoma, CASC15 may recruit EZH2, and EZH2 could subsequently directly bind to the promoter of PDCD4 in melanoma cells and inhibit PDCD4 expression." (PMID 31620370, 2019). "PDCD4, a tumor suppressor, was recently demonstrated to be negatively regulated by CASC15, via recruiting EZH2 and subsequently changing H3 K27me3 level in melanoma." (PMID 30519392, 2018). "PDCD4 S457 also participates in this regulatory mechanism in melanoma cells but, although phosphorylated, this site does not show a significant effect on PDCD4 degradation in MDA-MB-231 cells." (PMID 27028868, 2016). "Although we found an association between CD68+ macrophages and high PDCD4 expression using QIF, PDCD4 was not present at high levels in the macrophage (defined as CD14+/C1QA−) or microglia (defined as C1QA+) populations in our one sequenced melanoma brain metastasis sample." (PMID 33801444, 2021). "Our group reported prognostic significance of total PDCD4 protein levels (cytoplasmic and nuclear) by quantitative immunofluorescence (QIF) in a small cohort of melanoma metastases and shorter survival among patients with absent or low levels of PDCD4 in cerebral lesions." (PMID 33801444, 2021).
pancreatic cancer (25 papers, 2011 to 2025). "miR-429 enhanced the sensitivity of pancreatic cancer cells to gemcitabine by upregulating Akt-inhibited programmed cell death 4 (PDCD4)." (PMID 35682560, 2022). "Although PDCD4 showed an opposite decrease in pancreatic cancer tissues, it was consistent with the trend of MYEOV expression in different stages of pancreatic cancer." (PMID 36358856, 2022). "It was found that all genes except PDCD4 showed high expression in pancreatic cancer tissues, which was also consistent with our above findings." (PMID 36358856, 2022). "We analyzed mRNA expression levels of MYEOV, GPRC5A, KRAS, EGFR, SERPINB5, EIF4G2, and PDCD4 in pancreatic cancer tissues and normal tissues adjacent to pancreatic cancer from three pancreatic cancer patients." (PMID 36358856, 2022). "We also validated the role of ceRNA network genes such as GPRC5A, SERPINB5, KRAS, EGFR, EIF4G2, and PDCD4 in pancreatic cancer." (PMID 36358856, 2022). "miR-183, another member of the miR-182 family, also targets PDCD4 and induces cell proliferation, migration, and invasion in a pancreatic cancer cell line." (PMID 34525952, 2021). "In order to experimentally evaluate some of these miR-21 predicted targets in the context of pancreatic cancer, we selected PDCD4 and BTG2 from that list for being also highly down-regulated in PDAC (FC=-7.88 and FC=-5.53, respectively)." (PMID 29464088, 2018). "All the data confirm that miR‐21 plays an important role in 5‐FU resistance in pancreatic cancer by targeting PDCD4." (PMID 26864640, 2016). "Western Blot results indicated that transfection of PDCD4 can alleviate the reduction of PDCD4 which induced by miR-320a in pancreatic cancer cells." (PMID 27279541, 2016). "The rescue experiments indicated PDCD4 can rescue the phenotype by miR-320a gain of function and suggested that miR-320a played its function in drug-resistance of pancreatic cancer cells by targeting PDCD4." (PMID 27279541, 2016). "The protein levels of PDCD4 were substantially decreased after ectopic over-expression of miR-320a in pancreatic cancer PANC-1 and PATU8988 cell lines as evidenced by western blot assays." (PMID 27279541, 2016). "In this study, we firstly clarified miR-320a promoted pancreatic cancer cells proliferation and 5-FU resistance in pancreatic cancer cells by targeting PDCD4." (PMID 27279541, 2016). "Overexpression of PTEN and PDCD4 can attenuate the effects of miR‐21 on 5‐FU resistance in pancreatic cancer cells." (PMID 26864640, 2016). "Taken together, these findings indicate that PDCD4 can be negatively regulated by miR-320a, and miR-320a modulates 5-FU resistance in human pancreatic cancer cells by targeting PDCD4." (PMID 27279541, 2016). "As the first study to show that miR‐21 promotes resistance to 5‐FU in pancreatic cancer cells by targeting PDCD4 and PTEN, our research demonstrates that a reduction in miR‐21 is critical to increase sensitivity to 5‐FU." (PMID 26864640, 2016). "Additionally, miR-183-5p directly promotes PDCD4, a pro-apoptotic molecule, whereas miR-96 has been shown to act as a tumour suppressor in pancreatic cancer by regulating the oncogene KRAS." (PMID 39685620, 2024). "Similarly, miR-320a was found to be upregulated in 5-FU-resistant pancreatic cancer cells, causing induced mesenchymal phenotype, enhanced cell invasion and migration, and 5-FU resistance by binding to the 3′UTR of PDCD4 mRNA in pancreatic cancer." (PMID 38139352, 2023). "This implies that in contrast to the other six genes, PDCD4, although capable of acting as a tumor suppressor gene, may be suppressed in pancreatic cancer." (PMID 36358856, 2022). "It was noted that MYEOV could serve as a ceRNA by producing molecular sponging effects on hsa-miR-103a-3p and hsa-miR-107, thus affecting the role of GPRC5A, SERPINB5, EGFR, KRAS, EIF4G2, and PDCD4 on pancreatic cancer progression." (PMID 36358856, 2022).
pancreatic cancer (continued). "MiR-320a by targeting PDCD4 could promote 5-FU resistance in human pancreatic cancer cells via EMT regulation." (PMID 33954114, 2021). "miR-320a has been shown to promote 5-FU resistance to pancreatic cancer cells by targeting PDCD4 and most interestingly, miR-320b overexpression have been correlated to late stage chronic pancreatitis, linking this chronic inflammatory disease of pancreas to PDAC." (PMID 31795960, 2019). "In order to experimentally evaluate if some of these predicted targets could act as miR-21 targets in the context of pancreatic cancer, we selected 2 targets (PDCD4, BTG2) from the top miR-21 targets list." (PMID 29464088, 2018). "Whereas restoration of PDCD4 expression could partially attenuate the function of miR-320a in pancreatic cancer." (PMID 27279541, 2016). "To definitively determine whether miR‐21‐induced 5‐FU resistance was dependent on PDCD4, we performed rescue experiments with miR‐21 and PDCD4 overexpression plasmids in the two pancreatic cancer cell lines." (PMID 26864640, 2016). "PDCD4 is another target gene of miR‐21 in pancreatic cancer cells." (PMID 26864640, 2016). "Furthermore, we demonstrated that miR-320a was able to bind to 3′UTR of PDCD4 mRNA, and mediated its down-regulation in 5-FU resistance of human pancreatic cancer cells." (PMID 27279541, 2016). "So we speculated that miR-21 and miR-320a cooperatively contributed to drug-resistance of pancreatic cancer cells through down-regulating PDCD4 together." (PMID 27279541, 2016). "Meanwhile, restoration of PDCD4 expression could attenuate the 5-FU or gemcitabine resistance of pancreatic cancer cells induced by miR-320a." (PMID 27279541, 2016). "Taken together, our study demonstrated that miR-320a played important role in regulating 5-FU resistance by targeting PDCD4 and might be developed as new therapeutic target for pancreatic cancer." (PMID 27279541, 2016). "To further determine whether PDCD4 was a direct target of miR-320a in pancreatic cancer cells, we over-expressed miR-320a in the two pancreatic cancer cell lines and detected PDCD4 protein levels." (PMID 27279541, 2016). "Indeed, it has been shown in recent studies that these miRNAs are involved in regulating development of pancreatic cancer via specific target genes (PDCD4, NF-kappaB, TP53INP1)." (PMID 25071021, 2014). "To investigate whether MYEOV acts as ceRNA to exert certain regulatory effects on genes such as GPRC5A, SERPINB5, KRAS, EGFR, EIF4G2, and PDCD4, we analyzed the differential expression of these genes in pancreatic cancer and normal pancreatic tissues by the GEPIA database." (PMID 36358856, 2022). "MiR-21 by targeting PTEN and PDCD4 could increase resistance to 5-FU in pancreatic cancer cells." (PMID 33954114, 2021). "Moreover, upward regulation of PTEN and PDCD4 may weaken the effect of miR-21 on pancreatic cancer resistance on 5-FU." (PMID 34680441, 2021). "miR-320a may stimulate resistance to 5-FU by binding to 3′UTR mRNA PDCD4 in pancreatic cancer." (PMID 34680441, 2021). "To explore whether the promotion of miR-320a on drug-resistance in pancreatic cancer cells was dependent on targeting PDCD4, we performed rescue experiments through over-expressing PDCD4 in PANC-1 and PATU8988 cells infected with lentivirus expressing miR-320a." (PMID 27279541, 2016). "Previous studies in breast and pancreatic cancer cell lines have suggested that over expression of miR-21 may lead to increased cell proliferation and decreased apoptosis through the targeted degradation of tumor suppressor protein PDCD4." (PMID 21592394, 2011). "miR‐21 targets phosphatase and tensin homologue (PTEN), programed cell death 4 (PDCD4), tropomyosin 1 (TMP1), and tissue inhibitor of metalloproteinases 3 (TIMP3) genes in pancreatic cancer resulting in increased proliferation, invasion and chemoresistance." (PMID 39855897, 2025).